IL6 (interleukin 6)
Diseases named in the same sentence as IL6 in open-access papers (continued):
Sharing a sentence is not in itself a finding about the gene and the disease.
cancer (continued). "In addition, factors other than IL-6, released from the cancer cells, promoted IL-6 production from recruited MDSCs in the vicinity of cancer cells." (PMID 24021059, 2013). "Unbalanced IL-6 production has a role in several diseases, such as osteoporosis, atherosclerosis, autoimmune disorders, rheumatoid arthritis, psoriasis, diabetes, and cancer." (PMID 23738079, 2013). "Similar results were obtained with baseline IL-6 and sTNFR2 remaining as independent predictors of incident cancers, with HR of 1.53 (1.18-2.00, p=0.002) per natural log unit increase in IL-6, and 3.15 (1.53-6.47, p=0.002) per natural log unit increase in sTNFR2, respectively." (PMID 24205276, 2013). "Mokart and colleagues reported that IL-6 could be an early marker of postoperative SIRS in patients undergoing major surgery for cancer." (PMID 24124497, 2013). "Indeed, STAT3 is well known to be part of a pro-inflammatory loop involving IL-6 and NF-kB, thought to play an important role in inflammation-related cancer as well as in auto-immunity." (PMID 23460527, 2013). "Malignant tumors that produced IL-6 are designated as IL-6-producing tumors." (PMID 23710188, 2013). "We next evaluated whether IL-6-mediated MDSC recruitment promoted the metastasis of EMT6 cancer cells." (PMID 24021059, 2013). "The cytokines involved in cancer-related inflammation, including interleukin-6 (IL-6) and tumor necrosis factor-alpha (TNFα), may induce neutrophilia." (PMID 24223776, 2013). "IL-6 is produced by cancer cells, including PC, macrophages, lymphocytes, and endothelial cells." (PMID 23840582, 2013). "Treatment with pomegranate extracts may be successful in the therapeutic treatment of inflammatory disease and cancer since they have been shown to decrease the production of IL-6 and IL-8 and inhibit NF-κB in human mast cells and basophils." (PMID 23737845, 2013). "Some studies have compiled the possible roles of CRP in cancer development as follows: i) anti-apoptotic activity and tumorigenic potency by over expression of IL-6, ii) T cell impairment, iii) resistance to chemotherapy, and iv) increased levels of serum angiogenic factors." (PMID 23409924, 2013). "Furthermore, we were able to quantitate the increased NF-κB activity levels prior to the increase of plasma IL-6 levels in the perioperative period of major surgery for cancer." (PMID 24124497, 2013). "Cachexia in patients with PC and other cancers is also regulated by IL-6." (PMID 23840582, 2013). "In cancer cells, IL-6 induces chemoresistance through IL-6-STAT3 axis." (PMID 23592411, 2013). "Furthermore, there was a positive correlation between IL-6 overexpression and cancers developing loco-regional failure or distant metastasis." (PMID 23561329, 2013). "Plasma concentrations of YKL-40 and IL-6 are emerging as new biomarkers in patients with cancer." (PMID 23840582, 2013). "IL-6 is one of inflammatory cytokines and is well known as a cancer progression-related cytokine." (PMID 23592411, 2013). "IL-6 is one of the elements linking inflammation and angiogenesis in the course of cancers." (PMID 23554823, 2013). "In the peri-operative period all cancer patients showed a marked and significant increase in IL-6." (PMID 23374147, 2013). "In our model, increased EMT and/or cancer stem cell compartment upon IL6 stimulation could explain increased invasiveness and this remains to be investigated." (PMID 23369187, 2013). "We have previously shown that IL-6/Stat3/VEGF pathway plays an important role in cancer metastasis." (PMID 26082317, 2013). "Interleukin 6 (IL-6), a pro-inflammatory cytokine produced mainly by macrophages, could promote cancer cell EMT and invasion." (PMID 23922983, 2013). "Interestingly, the expression of IL-1α mRNA in fibroblasts by various cancer cell–conditioned media was comparable with IL-6 production by the same conditioned media." (PMID 23593346, 2013).
cancer (continued). "The higher level of p-STAT3 in cancer cells after the IL-6 treatment might account for a weaker response to enhanced STAT3 activation after EBV infection." (PMID 23658720, 2013). "Although QYHJ had an effect on cancer-related inflammation, i.e., an inhibition of TAM infiltration and IL-6 production, the precise underlying mechanism remains unknown." (PMID 23922983, 2013). "Therefore, HVJ-E-mediated eradication of cancer results from the activation of anti-cancer immunity by IL-6-mediated suppression of Tregs." (PMID 24369016, 2013). "The results of this study may provide new opportunities to improve efficacy of other types of vaccines and/or against other IL-6-producing cancers." (PMID 24156030, 2013). "PCa cells have upregulated expression of both IL-6 and its receptor IL-6R, as well as elevated circulating levels of IL-6 in patients with metastatic PCa and CRPCa, correlating IL-6 production to cancer morbidity and differential autocrine and paracrine modulation of PCa cell lines." (PMID 23738079, 2013). "Notably, IL-6 is a cytokine that can activate JAK2/STAT3 signaling in cancer cells, which has an important effect on oncogenesis." (PMID 23690956, 2013). "Increased IL-6 affects both cancer and lung fibroblast cells." (PMID 23592411, 2013). "There is evidence implicating IL-6 in cancer tumorigenesis through the STAT3 pathway." (PMID 23819063, 2013). "GTCs are widely recognized to exert cancer-preventive effects partly by inhibiting the expression of TNF-α and IL-6, indicating that the suppression of inflammation is one of the key mechanisms by which GTCs prevent cancer development." (PMID 25674420, 2013). "IL-6 has been reported to be a predictor in various cancers." (PMID 23637926, 2013). "Given that there are no known naturally occurring activating mutations in the STAT3 gene, aberrant activation of STAT3 in many types of cancers is primarily due to overexpression or deregulation of upstream signaling molecules such as IL-6/gp130, EGF/EGFR, JAK2, or Src." (PMID 24260381, 2013). "Mesenchymal stem cells constitute the cancer stem cell niche by providing IL-6 and CXCL7." (PMID 24021059, 2013). "To evaluate whether IL-6 could induce proliferation and metastasis of RCC cancer cells, we serum-starved A498 cells for 12 h and then cultured them in the absence or presence of IL-6 for 48 h." (PMID 23690956, 2013). "We studied if this capacity to overproduce IL-6 is regulated by cancer cell-independent mechanisms." (PMID 23517603, 2013). "This study may be a platform for improvement of other cancer vaccines by curcumin and against other IL-6-producing cancers." (PMID 24156030, 2013). "In addition, circulating IL-6 correlates with the reduction in testosterone in patients with cancer cachexia." (PMID 24285707, 2013). "Moreover, it was shown that when MDSCs were exposed to conditioned media of metastasizing cancer cells, MDSCs secreted exaggerated IL-6 and soluble IL-6Rα, which induced persistent activation of STAT3 in cancer cells." (PMID 24021059, 2013). "The PGE2 expression seemed to be related to the stem cell-inducing capacity of fibroblasts through autocrine mechanisms, including induction of IL-6 in fibroblasts, which would then act on cancer cells and promote the expansion of cells expressing a breast CSC signature (EpCAM+/CD24-/CD44+)." (PMID 22509805, 2012). "Among them, IL-6 is considered to be a key mediator in the pathogenesis of cancer cachexia." (PMID 23326296, 2012). "In addition, the cancer cells have been reported to express receptors to IL-6, MIP-2, KC, VEGF, MCP-1, and MIG." (PMID 22315691, 2012). "These basic and clinical indications strongly support our current findings that hochuekkito has the biological ability to inhibit the production of proinflammatory cytokines such as IL-6 by host cells and is effective and beneficial for the treatment of cancer cachexia." (PMID 23326296, 2012).
cancer (continued). "In addition, IL-6 is an interleukin that plays a key role in the pathophysiology of several cancers and various inflammatory disorders of the immune system." (PMID 22754319, 2012). "Indeed, our collaborators laboratory recently utilized IL-6 blockade through this same antibody to suppress the muscle protein degradation of cancer cachexia." (PMID 22716658, 2012). "XZH-5 could also inhibit interleukin-6-induced STAT3 phosphorylation in cancer cell lines expressing low phosphorylated STAT3." (PMID 23056374, 2012). "Similar to results found in IL-6, the fact that all patients in the study had Stage II cancer may explain the results found." (PMID 22811748, 2012). "Additionally, there is substantial evidence implicating a role of IL-6 in the pathogenesis of cancer cachexia." (PMID 22361433, 2012). "In addition, cancer associated fibroblasts, inflammatory cells (especially type-2 macrophages) and cytokines (e.g., IL-1β, TNF-α and IL-6) have been shown to affect the regulation of autophagy in cancer cells through induction of a metabolic stress." (PMID 22974323, 2012). "Recent studies have shown that IL-6 plays a primary role in the pathophysiology of cancer." (PMID 22134360, 2012). "And the concentration of IL-6 has linear correlation with the variances of cancer-related fatigue." (PMID 22203880, 2012). "We hypothesized that IL-6 promotes the generation of cancer cells with stem-like properties by induction of EMT." (PMID 22134360, 2012). "They demonstrated the role of STAT3 in IL6 mediated migration of the cancer cells through EMT." (PMID 22194851, 2011). "Fibrinogen expression was also increased in quadriceps as well as liver in response to administration of IL-6, suggesting this may be a general response to conditions of high IL-6 and not limited to cancer." (PMID 21799891, 2011). "Our results indicate that skeletal muscle may be a major physiological source of acute phase response proteins, both at baseline and in pathological conditions of high IL-6, including cancer." (PMID 21799891, 2011). "However, neoplastic ovarian cells also routinely overexpress IL-6 in vitro and greater amounts of IL-6 are present in the cystic fluid of malignant tumors when compared to cystic fluid of benign tumors." (PMID 21765834, 2011). "Autologous serum is a possibility but the serum of cancer patients might contain high levels of inhibitory cytokines such as IL-6 or IL-10 that could affect DC function." (PMID 22082029, 2011). "In addition to canonical pathways, casein kinase 2 (CK2) has also recently been reported downstream of IL-6 signaling in cancer." (PMID 21559372, 2011). "The effects of IL-6 in vivo may be augmented by the secretion of IL-1, which has been shown to increase the expression of IL-6 by colon-26 carcinoma cells." (PMID 21832306, 2011). "Because the IL-6 feed-forward loop plays important role in the pathogenesis of inflammation-induced cancer as well as the drug resistance of cancer cells, the regulation of Stat3 could potentially be used to suppress IL-6 autocrine production in cancer cells." (PMID 21122157, 2010). "Obviously, the magnitude of immune cell infiltration might also have an indispensable role in the complex interactions between IL-6 and sIL-6R in cancer stroma, because IL-6, IL-1β, and in part sIL-6R are produced by cancer cells, as well as by immune cells." (PMID 20823887, 2010). "In another study on oesophageal carcinoma it has been suggested that IL-6 may contribute to cancer progression in an autocrine or paracrine manner acting as an antiapoptotic factor." (PMID 20565793, 2010). "Thus, STAT3 and Smad3 sequential activities in the cancer cells depended on IL-6 and TGF-β secreted in the supernatant and required NF-κB activity." (PMID 20520770, 2010). "Therefore, Jak2/Stat3, MEK/Erk and PI3-K/Akt pathways individually contribute to the regulation of IL-6 autocrine production in cancer cells." (PMID 21122157, 2010).
cancer (continued). "TNF-α, IL-1 and IL-6 are key cytokines involved in cancer-related cachexia." (PMID 20920199, 2010). "Our biochemical and genetic studies clearly demonstrated that Jak2/Stat3, in combination with other IL-6 downstream pathways, contributed frequently and substantially to IL-6 autocrine production in a broad spectrum of cancer cell lines as well as in clinical cancer samples." (PMID 21122157, 2010). "For example, NF-κB-mediated IL-6 promotes cancer cell proliferation and invasion." (PMID 20520770, 2010). "In other words, the observed increase in IL-6 secretion in the cocultures may be produced by the cancer cells themselves." (PMID 20637124, 2010). "Studies not directly investigating the role of Stat3 on the expression of IL-6 in cancer cells have found some evidence suggesting Stat3 may increase IL-6 expression." (PMID 21122157, 2010). "Cocktail 1 was designed as in a previous reported cocktail, where the combination of poly I:C, IFNα, IFNγ, TNFγ and IL-1β showed very potent IL-12p70 stimulating properties compared to the standard DC cocktail used for DC based cancer vaccines, containing IL-6, TNFα, IL-1β and PGE2." (PMID 20663192, 2010). "IL-6 has an immunosuppressive role in cancer patients by inhibiting the development of DCs." (PMID 20565840, 2010). "TGFβ and IL-6 are closely related to the invasion and metastasis of cancer." (PMID 20565840, 2010). "To find out whether IL-6 would be regulated by Stat3 in cancer cell lines other than AS2, we performed genetic siRNA experiments on two drug resistant cancer cell lines (KB-CPT100 and MCF-7/ADR)." (PMID 21122157, 2010). "Our findings suggest that Stat3 could potentially be regulated to suppress IL-6 autocrine production in cancer cells to inhibit the progression of cancer and reduce drug resistance." (PMID 21122157, 2010). "There is concern that intervention to prevent radiation-induced toxicity may also serve to protect cancer because clinical investigations found increased serum IL-6 levels in cancer patients." (PMID 20374625, 2010). "Although the effect of IL-6 to cancer is still unknown, this cytokine may provide a link from bacterial infection to inflammation and cancer." (PMID 21047437, 2010). "Similarly, AG490 treatment also decreased the IL-6 secretion in various drug resistant cancer cells exhibiting constitutively active Stat3." (PMID 21122157, 2010). "Through this self-synthesis, the secreted IL-6 may induce further IL-6 production in cancer cells in which IL-6 is commonly produced." (PMID 21122157, 2010). "Thus, we designed a series of biochemical and genetic studies of various established cancer cell lines and clinically isolated cancer cells to directly investigate the regulatory role of Stat3 on IL-6." (PMID 21122157, 2010). "Interleukin-6 is synthesised with a signal peptide, which generally leads to co-translational transport into the endoplasmic reticulum which may explain our immunohistochemical results that IL-6 mainly exists in the cytoplasm of cancer cells." (PMID 20823887, 2010). "With a potential influence on physical, social, and emotional functioning, symptom researchers may wish to consider evaluating the influence of IL-6 activity on cooccuring symptoms in cancer." (PMID 21994811, 2010). "Our knock-down studies of AS2, MCF-7/ADR, and KC-CPT100 cells and our pharmacological inhibition experiments with seven established cell lines and 20 clinical samples revealed that Stat3 did in fact affect expression of IL-6 in most of the cancer cells we tested." (PMID 21122157, 2010). "By targeting Stat3, we may directly inhibit Stat3-dependent drug resistant mechanisms and inhibit Stat3-independent drug resistant mechanisms indirectly by decreasing IL-6 autocrine production in cancer cells simultaneously." (PMID 21122157, 2010).
cancer (continued). "The median level of IL-6 increased proportionally with the stage of the cancer (the median level of IL-6 in stage I 7.36 ± 5.52 pg/ml, stage II 7.66 ± 2.24 pg/ml, stage III 11.87 ± 14.90 pg/ml and stage IV 13.92 ± 10.76 pg/ml), and this difference was statistically significant (P < 0.001)." (PMID 19457231, 2009). "Interleukin-6 (LI-6) is an important growth and survival factor by the regulation of phosphatidylinositol 3-kinase signaling pathway in the initiation and progression of human cancers." (PMID 19338666, 2009). "We investigated whether monoclonal antibodies directed against IL-6 may enable to reverse resistance of cancer cell lines." (PMID 19956602, 2009). "In cancer, IL-6 is generally known to be involved in host defense mechanisms." (PMID 19457231, 2009). "In humans, there is an increasing evidence that cytokines, including tumor necrosis factor alpha (TNF-α), interleukin (IL)-1, IL-6, IL-8 and interferon gamma (IFN-γ) may participate in the cause or the development of cancer cachexia." (PMID 20037740, 2009). "For example, androgen withdrawal-induced marked downregulation of relaxin, VEGF, vimentin and BMP-6, involved in cancer progression as well as upregulation of cellular retinol binding protein 7 and interferon-γ receptor, negatively regulating cancer progression, in LNCaP/IL-6#1." (PMID 19844233, 2009). "Likewise, STAT3 binding to the predicted TFBSs has been experimentally verified in IL-6 stimulated human cancer cell lines." (PMID 19730699, 2009). "The pro-inflammatory cytokines TNF-α, IL-1 and IL-6, by contrast, may promote cancer progression by a variety of other mechanisms, that are only now beginning to be elucidated." (PMID 18682839, 2008). "IL-6 may, e.g., act as an autocrine or paracrine growth factor, but also as an anti-apoptotic agent on cancer cells, as is the case in oral cancer." (PMID 18234094, 2008). "Recombinant human IL-6 has been given by subcutaneous and intravenous injection to human subjects as part of Phase I/II clinical trials performed to examine its potential thrombopoietic effects following cancer chemotherapy." (PMID 18270592, 2008). "IL-6 activates Stat3, which has previously been demonstrated to activate the transcription of several anti-apoptotic genes and to contribute to apoptosis resistance in cancer cells." (PMID 18270592, 2008). "In fact, different data regarding the relation between IL-6 and cancer are known." (PMID 17288583, 2007). "Proteolysis-inducing factor has also been shown to activate NF-κB in primary hepatocytes and the human cancer cell line HepG2, resulting in the increased production of interleukin-6 and -8 (IL-6 and IL-8) and C-reactive protein and the decreased production of transferrin." (PMID 15714207, 2005). "At baseline, compared with the healthy subjects, cancer patients had less weight and fat mass (P<0.05) and had lower circulating concentrations of leptin (P<0.05), but higher concentrations of cortisol and interleukin-6 (P<0.05)." (PMID 15026790, 2004). "IL-6 is known to promote the proliferation and metastatic potential of cancer cells." (PMID 15150588, 2004). "In the cancer patients neither sIL-6R nor sgp130 concentrations were significantly associated with either IL-6 or C-reactive protein concentrations." (PMID 15570310, 2004). "However, an infusion of interleukin-6 has been shown to increase cortisol concentrations and fat oxidation in cancer patients." (PMID 15026790, 2004). "In human cancer, the −174 G/C IL-6 polymorphism does not appear to be a risk factor for the development of multiple myeloma or melanoma." (PMID 14735187, 2004). "Interestingly, recent studies confirm the role of IL-6 in promoting angiogenesis and cancer progression." (PMID 14562010, 2003). "However, the available information about the source and the pathophysiological regulation of IL-6 in cancer cells is limited." (PMID 10408408, 1999).